CTLA4 (cytotoxic T-lymphocyte associated protein 4)
Diseases named in the same sentence as CTLA4 in open-access papers (continued):
Sharing a sentence is not in itself a finding about the gene and the disease.
B-cell lymphoma (33 papers, 2011 to 2026). "Another example is that Tregs were associated with good outcome in B-cell lymphoma when they were identified by Foxp3 alone, but Tregs were associated with poor patient outcome when they were identified by both CTLA-4 and Foxp3." (PMID 33086518, 2020). "This study suggested that PD-1 and CTLA-4 might be associated with the suppression of antitumor immunity in dogs with B cell lymphoma, and particularly through CD4+ T cells." (PMID 30040869, 2018). "In the present study, we demonstrate that blocking STAT3 through locally delivered CpG-Stat3 siRNA enhances the efficacies of the systemic PD-1 and CTLA4 blockade against mouse A20 B cell lymphoma." (PMID 39618825, 2024). "Silencing Stat3 through locally delivered CpG-Stat3 siRNA significantly enhanced the antitumor efficacies of systemic administration of PD-1- and CTLA4-specific antibodies in mice bearing the A20 B cell lymphoma arresting tumor growth." (PMID 39618825, 2024). "In B cells, CTLA4-induced immune suppression occurs predominantly via intrinsic STAT3 activation, and CTLA4 is critical for B-cell lymphoma proliferation and survival." (PMID 35455289, 2022). "Emerging evidence suggests that anti-CTLA-4 agents synergizes with anti-CD20 mAbs in treating R/R B-cell lymphoma." (PMID 34404434, 2021). "In B-cell lymphoma cells, binding of the CD86 ligand to cytotoxic T-lymphocyte-associated antigen 4 (CTLA4) results in recruitment and phosphorylation of TYK2, which activates STAT3 to drive transcription of genes promoting tumor growth and survival." (PMID 34439323, 2021). "Early results from a pilot study showed that CTLA4 Ig-primed donor lymphocyte infusion (DLI) treatment results in progression-free survival in refractory aggressive B-cell lymphoma patients." (PMID 32265918, 2020). "They further demonstrated the role of CTLA-4 in Tregs within advanced B-cell lymphoma in limiting anti-CD20-mediated tumor regression." (PMID 30533489, 2018). "Recently, we have shown that CTLA4-FasL can induce robust apoptosis of B cell lymphoma cell lines by activating pro-apoptotic signals in parallel to abrogating anti-apoptotic ones." (PMID 25227919, 2014). "In the present study, we present data suggesting that CTLA4-FasL naturally forms a stable and soluble homo-hexamer and propose a unique mode-of-action model for the treatment of B cell lymphoma." (PMID 25227919, 2014). "In contrast, the JY and Raji B cell lymphoma cell lines, shown to be highly sensitive to CTLA4-FasL, express high levels of CD80, CD86 and CD95." (PMID 25227919, 2014). "We believe that this combination of properties, make CTLA4-FasL an extremely potent apoptosis inducer of B7 expressing tumors, such as B cell lymphomas." (PMID 25227919, 2014). "Similarly, CTLA‐4 inhibition—either alone or in combination with PD‐1 blockade—has yielded limited clinical activity in B‐cell lymphomas, further underscoring the restricted efficacy of checkpoint inhibition in this disease." (PMID 41492119, 2026). "We next tested whether combining CpG-Stat3 siRNA with CTLA4 or PD-1 inhibition would lead to superior antitumor effects relative to the single agents in the mouse B cell lymphoma." (PMID 39618825, 2024). "However, the clinical benefit of immunotherapy based on CTLA-4-specific antibodies in B cell lymphoma diseases, even in combination with other monoclonal antibodies, is low." (PMID 38340727, 2024). "Here, we assessed whether silencing Stat3 with CpG-Stat3 siRNA can significantly enhance the efficacies of CTLA4 antibody therapy in B cell lymphoma by augmenting the immunostimulatory effects." (PMID 39618825, 2024). "B cell lymphoma-derived exosomes upregulated inhibitory receptors PD-1 (programmed cell death protein 1), CTLA-4 (cytotoxic T lymphocyte-associated antigen-4) and BTLA (B- and T-lymphocyte attenuator), and induced apoptosis of T cells through activation of Fas/Fas ligand pathway." (PMID 37182123, 2023).
B-cell lymphoma (continued). "Results from recent clinical trials have shown that CTLA-4 alone or in combination with other agents exert a positive effect in the treatment of melanoma, but further investigations of the application in B-cell lymphoma are warranted." (PMID 34404434, 2021). "CTLA-4 is expressed on regulatory T (Treg) cells and is believed to act as an immune checkpoint receptor, which contributes to the inhibition and exhaustion of T-cells, and has an additional role in promoting the proliferation and survival of B-cell lymphoma." (PMID 34079795, 2021). "Notably, the efficient apoptotic activity induced by CTLA4-FasL is highly specific for human B cell lymphoma cells that express both a functional Fas receptor and B7 receptors, supporting the notion that more than one biological signaling pathway are involved." (PMID 25227919, 2014). "Recently, CTLA4-FasL, that can bind to B7 and Fas receptor (Fas), was shown to induce robust apoptosis of cell lines originating from B cell lymphomas expressing both B7 and Fas, by activating pro-apoptotic signals in parallel to abrogating anti-apoptotic ones." (PMID 25227919, 2014). "In B-cell lymphoma, its potency stems from the combination of its synergistic effect of activating the caspases while abrogating the anti-apoptotic signaling, with its unique hexameric structure, making CTLA4-FasL a promising candidate for aggressive B cell lymphomas treatment." (PMID 25227919, 2014). "They then demonstrated that intratumoral injections of the vaccine could overcome resistance and synergize with anti-CTLA-4 and anti-PD-L1 antibodies in four different models (Neuro2a neuroblastoma, A20 B-cell lymphoma, EMT6 breast mammary carcinoma and CT26 colon carcinoma)." (PMID 34055652, 2021). "In human medicine, several clinical trials using ipilimumab, which blocks the CTLA-4 signal or CTLA-4 inhibitors, have been widely reported and offered prolonged survival with manageable side effects in patients with B-cell lymphoma." (PMID 37884996, 2023). "We found that B-cell lymphoma (BCL) patients have dysregulated expression of intracellular and extracellular HSPs, immune checkpoints PD-1, CTLA-4, and STAT3 in CD3/CD28-activated T cells." (PMID 36359267, 2022). "Anti-CTLA-4 and anti-CD20 combined treatment overcomes adaptive resistance and prevents relapse in the mouse B-cell lymphoma model." (PMID 30533489, 2018). "In contrast, the expression levels of CTLA-4 and GITR in Treg of PB, BM and involved lymphatic tissues from B-cell NHL were significantly higher than those in PB samples from HVs and benign LNs." (PMID 22174855, 2011). "In a final experiment, the combination of intratumoral rotavirus vaccine and systemic anti-CTLA-4 antibody cured all mice with complete regressions of both injected and non-injected tumors in both the neuroblastoma and the B-cell lymphoma models." (PMID 34055652, 2021). "Thus, anti-CTLA-4 and anti-CD20 combined treatment is a possible new clinical strategy in overcoming adaptive resistance and preventing relapse of B-cell lymphoma." (PMID 30533489, 2018). "Furthermore, the expression levels of CTLA-4 and GITR in Treg from involved lymphatic tissues were slightly higher than those from PB or BM in patients with B-cell NHL." (PMID 22174855, 2011). "These cells are enriched in negative immune regulators like CTLA-4 and therefore CTLA-4 blockade with ipilimumab was studied in a phase 1 trial for patients with relapsed/refractory B cell NHL." (PMID 38322418, 2024).
Hashimoto thyroiditis (33 papers, 2004 to 2025). An autoimmune disorder caused by the production of autoantibodies against thyroid tissue. "Cytotoxic T-lymphocyte-associated antigen 4 (CTLA-4) is one of the immune regulatory genes that correlates with Hashimoto's thyroiditis (HT)." (PMID 36724016, 2023). "Our results along with previous studies suggest that the CTLA4 gene on chromosome 2q33 is a susceptibility locus for autoimmune hypothyroidism." (PMID 26963610, 2016). "The genetic factors which are associated with Hashimoto's thyroiditis lie in the human leukocyte antigen (HLA) complex, while an association with cytotoxic T-lymphocyte-associated protein 4 (CTLA-4) or a closely linked gene has also been described." (PMID 27429616, 2016). "Furthermore, to evaluate the possible expression dysregulation of CTLA4 variants, which are important in T regulatory cell’s function, the mRNA levels of flCTLA4 and sCTLA4 genes were measured in patients with autoimmune hypothyroidism and compared with those from controls." (PMID 26963610, 2016). "Our results suggest +49A/G and CT60 polymorphism of CTLA4 and E33 polymorphism of TG may be genetic risk factors for autoimmune hypothyroidism susceptibility and down regulation of both forms of CTLA4 advocates the crucial role of CTLA4 in pathogenesis of autoimmune hypothyroidism." (PMID 26963610, 2016). "Cytotoxic T-Lymphocyte Antigen-4 (CTLA-4) is an immune checkpoint receptor expressed on T cells, and in Hashimoto’s thyroiditis the overexpression of CTLA-4 on dysfunctional immune cells is a key factor in disease progression." (PMID 41476603, 2025). "In autoimmune diseases such as Hashimoto’s thyroiditis, CTLA-4 dysfunction has been shown to be a key factor in the progression of these diseases." (PMID 41476603, 2025). "HLA-DR3, cytotoxic T-lymphocyte-associated protein 4 (CTLA-4), and the TSHR genes were shown to be major susceptibility genes for GD and Hashimoto’s thyroiditis (HT) using the candidate gene approach." (PMID 31066758, 2019). "Comparison of the findings showed significantly decreased expression of both full length and soluble CTLA4 in autoimmune hypothyroidism patients than in controls after normalization with GAPDH expression (p< 0.0001 and p = 0.01 respectively)." (PMID 26963610, 2016). "Association studies for CTLA4 gene exon 1 +49A/G and 3’UTR CT60A/G polymorphisms and TG gene exon 33 polymorphism in autoimmune hypothyroidism patients." (PMID 26963610, 2016). "Distribution of haplotypes frequencies for CTLA4 gene polymorphisms (+49A/G and CT60A/G) among autoimmune hypothyroidism patients and controls." (PMID 26963610, 2016). "The cytotoxic T-lymphocyte antigen 4 (CTLA4) and thyroglobulin (TG) genes have been considered to be major genetic factors involved in the development of autoimmune hypothyroidism." (PMID 26963610, 2016). "Our findings show that the +49A/G and 3’ UTR CT60A/G polymorphisms of the CTLA4 gene influence both full length and soluble CTLA4 mRNA expression levels in patients with autoimmune hypothyroidism." (PMID 26963610, 2016). "This suggests variations at the genetic level, at least in part, could lead to the dysregulation of CTLA4 expressions in autoimmune hypothyroidism patients and supports the autoimmune pathogenesis of the disease." (PMID 26963610, 2016). "Candidate gene studies have also suggested links between autoimmune hypothyroidism and PTPN22 (protein tyrosine phosphatase, non-receptor type 22 (lymphoid)), as well as the HLA (human leukocyte antigen) class II region, CTLA4 (cytotoxic T lymphocyte antigen 4), and 8q23-24." (PMID 22493691, 2012).
clear cell renal cell carcinoma (31 papers, 2014 to 2025). "HIF1A-HIF2A, mTOR, CD27-CD70, CTLA4, PD-1, PD-L1, and PD-L2 are important biomarkers linked to drug resistance in metastatic Clear Cell Renal Cell Carcinoma (ccRCC)." (PMID 39796121, 2024). "A 26-year old male with metastatic clear cell renal cell carcinoma was started on treatment with the anti-programmed cell death-1 monoclonal antibody (anti-PD-1 mAb) nivolumab, followed by combined nivolumab and the anti-cytotoxic T-lymphocyte-associated protein 4 (CTLA-4) mAb, ipilimumab." (PMID 31511065, 2019). "Immunotherapies targeting PD-1 and CTLA-4 are key components of the treatment of metastatic clear cell renal cell carcinoma (mccRCC)." (PMID 39953623, 2025). "In clear cell renal cell carcinoma (ccRCC), first-line treatment combines nivolumab (anti-PD-1) and ipilimumab (anti-CTLA4), yielding long-term remissions but with only a 40% success rate." (PMID 38504270, 2024). "Three immune molecular subtypes of renal clear cell carcinoma based on CTLA-4, PD-1/PD-L1, CMTM6 and CMTM4 were found with different clinical and immunological characteristics." (PMID 35986302, 2022). "Furthermore, immune checkpoint inhibitors, encompassing those targeting CTLA-4 and PD-1, have demonstrated their capacity to incite tumorigenic reactions within the realm of renal clear cell carcinoma." (PMID 38162499, 2023). "Also, our group described significantly lower CD4+, CD8+, and CD45+ infiltrates in CTLA4 promoter hypermethylated clear cell renal cell carcinomas." (PMID 37415208, 2023). "The aim of this review is to update on the relative efficacy of combined cabozantinib + nivolumab therapy with other immune checkpoint inhibitors combined with TKIs or monoclonal antibodies blocking the CTLA-4 for the first-line treatment of metastatic clear-cell renal cell carcinoma." (PMID 36937206, 2022). "This systematic review updated on relative efficacy of different combination therapies (tyrosine kinase inhibitors or monoclonal antibodies blocking the CTLA-4 combined with immune checkpoint inhibitors) for the first-line treatment of metastatic clear-cell renal cell carcinoma." (PMID 36937206, 2022). "Studies on clear cell renal cell cancer suggested that exhausted immune cells and the lack of PD-1, PD-L1, and CTLA-4 expressions could underline the non-responsiveness to immunotherapy." (PMID 40264779, 2025). "Also, CTLA4 can serve as a prognostic biomarker for clear cell renal cell carcinoma." (PMID 39279987, 2022). "In renal clear cell carcinoma, TRPV3 can induce the expression of immune checkpoints such as LAG3, CTLA4, PDCD1, and TIGIT, leading to the accumulation of immunosuppressive T cells in the tumor microenvironment." (PMID 41331166, 2025). "We discovered that ACSL3 is substantially associated with the immune checkpoint inhibitors PD-1, PD-L1, CTLA4, LAG3, and HAVCR2 in renal clear cell carcinoma." (PMID 36338658, 2022). "However, its application in clear cell renal cell carcinoma (ccRCC) is limited due to the therapy response, and the prognostic value of CTLA4 in ccRCC has not been investigated in detail." (PMID 33117084, 2020).
kidney cancer (31 papers, 2016 to 2025). Primary or metastatic malignant neoplasm involving the kidney. "Research has shown that in the TME, TAMs promote FOXP3 and cytotoxic T-lymphocyte associated protein 4 (CTLA-4) expression in T cells, which happens to be an immune escape mechanism of kidney cancer." (PMID 39169402, 2024). "Common immune checkpoints in kidney cancer (PD-1, CTLA4 and LAG3) were more significantly expressed in the high-risk group." (PMID 38546385, 2024). "Additionally, we also identified that lower expression of several rhythm genes is associated with the sensitivity of combined anti‐PD1 and anti‐CTLA4 therapy in the kidney cancer animal model." (PMID 31927791, 2020). "Specifically, these individuals were more likely to be women, white, have kidney cancer, and be treated with combination anti-PD1 plus anti-CTLA4 treatment." (PMID 35072744, 2022). "Kidney cancer is a highly immunogenic tumor in which the tumor cells produce an immunosuppressive environment through a variety of mechanisms, such as increased expression of immunosuppressive molecules(PDCD1, CD274, CTLA4) in the TME and the occurrence of immune escape." (PMID 35860566, 2022).
esophageal cancer (30 papers, 2014 to 2025). A primary or metastatic malignant neoplasm involving the esophagus. "Immune checkpoint inhibitor (ICI) therapies have been evaluated for their effect on specific microbes in esophageal cancer, including cytotoxic T lymphocyte-associated protein 4 (CTLA-4) and programmed cell death 1 (PD-1)/PD-1 ligand (PD-L1) inhibitors." (PMID 36845103, 2023). "In agree with our results, univariate analysis demonstrates that higher tumor CTLA-4 expression is associated with shorter OS and poorer prognosis of patients with esophageal cancers." (PMID 29682176, 2018). "We first performed a hospital based case-control study to measure this association of esophageal cancer with CTLA-4 -1722T/C polymorphism in Han Chinese population, and then carried out a meta-analysis to obtain a comprehensive evaluation for this issue." (PMID 24710335, 2014). "First, this is to date the first case-control study detecting the association of CTLA-4 gene -1722T/C polymorphism with esophageal cancer." (PMID 24710335, 2014). "To further investigate this potential relationship, we decided to evaluate the association of CTLA-4 -1722T/C polymorphism with esophageal cancer risk in a hospital based case-control study, and then performed a comprehensive meta-analysis to derive a more precise result." (PMID 24710335, 2014). "Fuse the deglycosylated antibody with a CTLA-4 inhibitor to form a bifunctional macromolecule, achieving the dual effects of increased T-cell infiltration and tumor metabolism inhibition in an esophageal cancer model, with a complete remission rate of 40%." (PMID 41030448, 2025). "In conclusion, mIF profiling of the immune landscape in pretreatment biopsy samples of esophageal cancer identified HLA-DR and CD8/CTLA-4 positivity to be significantly associated with TTP and DSS." (PMID 39751903, 2025). "Recent studies have shown drugs targeting PD-1 and CTLA-4, cell surface proteins that inhibit immune response, to be effective in treating locally advanced, unresectable, metastatic esophageal cancer." (PMID 40075698, 2025). "Zinc finger protein 64 (ZFP64) is a transcription factor for cytotoxic T-lymphocyte-associated protein 4 (CTLA-4) and anti- PD-1 in esophageal cancer." (PMID 38915413, 2024). "The CTLA-4 blockade has become a progressive treatment strategy and has opened up an exciting way for cancer management, including esophageal cancer." (PMID 31485274, 2019). "In one study, CTLA-4 expression in esophageal cancers has been shown to have potential prognostic value." (PMID 29672601, 2018). "We found CTLA-4 expression in primary esophageal cancer lesions to have potential prognostic value, with higher CTLA-4 expression and higher density of interstitial CTLA-4+ lymphocytes associated with poorer prognosis." (PMID 27050369, 2016). "Analysis of CTLA-4 expression profiles in lymphocytes and tumor cells revealed marked variation among esophageal cancer patients." (PMID 27050369, 2016). "CTLA-4 was detected in the cytoplasm and cell membranes of esophageal cancer cells and in interstitial lymphocytes." (PMID 27050369, 2016). "However, as is the case with PD-1 and CTLA-4 inhibitors, further studies must be conducted to fully illuminate the safety and efficacy of these therapies for patients with esophageal cancer." (PMID 40075698, 2025). "Furthermore, there is no established functional or causal relationship between CTLA-4 expression in tumors and immune cells in the tumor microenvironment, or in patient prognosis, in esophageal cancer." (PMID 27050369, 2016). "In addition, CTLA-4 profiles may be useful for predicting the benefits and toxicity of CTLA-4 blockade in patients with esophageal carcinoma." (PMID 27050369, 2016). "The CTLA-4 -1722T/C polymorphism has not been investigated in esophageal cancer." (PMID 24710335, 2014). "At the same time esophageal cancer cells generate inhibitory signals and proteins, including PD-L1/2, VISTA, CTLA-4, LAG-3, and TIM-3." (PMID 40136652, 2025).